CD4 (CD4 molecule)
Diseases named in the same sentence as CD4 in open-access papers (continued):
Sharing a sentence is not in itself a finding about the gene and the disease.
tumor (continued). "We have shown previously that CD4+ T cells bearing an MHC-I–restricted TCR (F5) can enhance the antitumor activity of CD8+ T cells bearing the same TCR using a model Ag that is tumor-specific and not expressed in normal tissues." (PMID 25539815, 2015). "Therapeutic DC vaccines 2/LF and 2/LF/RNA did not affect CD4+ cell content during tumor development." (PMID 26325576, 2015). "Moreover, adoptive transfer of CD4+ T cells overexpressing Smad7, an intracellular inhibitor of TGF-β signaling, resulted in increased number of tumor-infiltrating Th17/Th1 hybrid cells and inhibition of tumor growth." (PMID 26583099, 2015). "Furthermore, results from clinical cancer patients showed that CD4/CD8 ratios were strongly positively correlated with the advanced tumor stage, large tumor sizes and positive lymph node status, but negatively correlated with RFS and OS." (PMID 25968569, 2015). "In general, BPDCN can only be diagnosed when the tumor cells demonstrate a blastic morphology, a CD4+/CD56+ immunophenotype, and no myeloid and T or B cell-specific surface marker expression." (PMID 25663917, 2015). "Docetaxel significantly reduced the number of MDSC and Tregs in spleen of tumor-bearing mice, while the numbers of CD4+ T cells, CD8+ T cells and NK cells were not changed." (PMID 25797259, 2015). "Some experiments have shown that in the absence of CD8+ T cells, CD4+ T cells can eliminate the tumor cells; however, effective tumor elimination needs both CD4+ and CD8+ T cells." (PMID 25605488, 2015). "Smoking patients with NSCLC had a significantly greater number of tumor stroma-infiltrating CD4+ T cells than nonsmokers with NSCLC (P < 0.05)." (PMID 26604855, 2015). "Tumour-infiltrating CD4+ T cells recognize antigens presented through MHC II, by conventional antigen-presenting cells (dendritic cells, B lymphocytes and macrophages), able to capture, process and present tumour antigens derived by cancer cells." (PMID 26081906, 2015). "One common approach to stimulate CD4 T cell helper response is the use of xenogenic or non-tumor antigens that recall immune memory or provide a non-specific help." (PMID 26350591, 2015). "The proportion of infiltrated CXCR5+CD4+ T cells was significantly decreased in tumor regions compared with nontumor regions." (PMID 25689070, 2015). "To investigate whether TLR7 ligand has an effect on the suppressive functions of Tregs, we next purified naïve CD4+CD25−T cells, CD4+CD25+ (regulatory) T cells and DCs by magnetic-activated cell sorting from wild type mice and tumor-bearing mice." (PMID 25593198, 2015). "Indeed, we found that CD4+ T cells primed in aged mice were ineffective in supporting cognate CD8+ T-cell responses, resulting in poor control of tumour progression in aged mice." (PMID 25850032, 2015). "It was previously reported that INFα increases function of CD4 effector T-cells, CD8+ T-cells and B-cells and that it may exert anti-tumor effects." (PMID 27708986, 2015). "In this way, the proliferation and activation of CD4+ T cells and CD8+ T cells may be enhanced, which then activates the anti-tumor immune response." (PMID 25815463, 2015). "T cells, specifically CD4+ and CD8+ T cells, are key players in tumor protective immunity." (PMID 25629611, 2015). "In addition, we observed increased PD-1 expression on CD4+ T and CD8+ T cells that were isolated from the spleen and tumour tissues of tumour-bearing mice compared with those isolated from naïve mice." (PMID 26581194, 2015). "Although T cell-NF-κB has been implicated by us and by others in the survival and proliferation of conventional T cells in other model systems, our current results indicate that tumor-specific CD4-cre x IKKβfl/fl CD8+ T cells were able to expand and accumulate in tumor-bearing mice." (PMID 25648675, 2015).
tumor (continued). "Prominent increases in NP8 tumor mice were found in the fractions of CD25+ cells, which could explain the enhanced frequency of CD4+ T cells in NP8 tumor compared to wtBALB/c mice, as CD25+ cells also include CD4+ regulatory T-cells." (PMID 26513294, 2015). "Furthermore, SUSD4 is expressed by CD4+ and CD8+ T cells in tumor stroma, which correlates with good prognosis." (PMID 26480818, 2015). "We have shown that the IFN-γ production by CD4 T cells against tumor was not a perfect marker of direct tumoricidal activity of these cells." (PMID 26538233, 2015). "At euthanasia, the C-ter-J28+-mDC-vaccinated recipients challenged with Panc02 displayed high expansion of CD4+- and CD8+-T-cells expressing granzyme B (more than 44%) in spleen compared to mDC-recipients (less than 10%) and a PBS-control mouse with late tumor development (2.5%) (5C)." (PMID 26405163, 2015). "In humans, a substantial proportion of tumor-infiltrating CD4 T cells express OX40, presumably due to recognition of tumor antigens, and the frequency of OX40+ CD4 T cells may be prognostic for patient outcomes." (PMID 25763356, 2015). "In addition, tumor infiltrating mononuclear cells (TIMC) and T cell subpopulations (CD4, CD8, T-bet and FoxP-3) were quantified." (PMID 26496037, 2015). "In the control group of prophylactic scheme (non-treated animals with Krebs-2) CD4+ content slightly varied during tumor development." (PMID 26325576, 2015). "However, in the presence of CD4+ helper cells, the level of CD8+ T cell reconstitution that occurs in these animals appeared sufficient to control tumor growth." (PMID 25901284, 2015). "As Apc/Min+ iTreg that were generated from naïve CD4 T cells that did not encounter tumor microenvironment, it also suggests that both nTregs and iTregs in Apc/Min+ mice are impaired in tumor inhibition function in an altered thymic development." (PMID 26146642, 2015). "When the functionality of splenic immune cells from tumor bearing mice was examined, it was observed that 4T1-bearing mice treated with MVA-TWIST/TRICOM exhibited improved CD4+ T-cell proliferation and CD8+ T-cell secretion of IFN-γ in response to Twist peptide compared to untreated animals." (PMID 26317648, 2015). "Moreover, reinfusion of CD4+CD25+ T cells in tumor-bearing mice, pre-treated with low-dose cyclophosphamide, abrogated the anti-tumor effect of the drug, emphasizing that Tregs counteract the therapeutic efficacy of the drug." (PMID 26500653, 2015). "Interestingly, we also observed a CD4+CD25−FoxP3+ tumour cell population, which was also significantly reduced in the pEEVGmCSF-b7.1-treated animals when compared with untreated tumours (P<0.05), and also in the therapeutic control pGT141GmCSF-b7.1." (PMID 25373914, 2015). "The degree of CD4+ T cell proliferation achieved in response to Twist peptide after treatment with MVA-TWIST/TRICOM was very similar between tumor bearing and non-tumor bearing animals, however, the degree of background response was much higher in non-tumor bearing mice." (PMID 26317648, 2015). "There is growing evidence that supports the existence of elevated numbers of Tregs in tumours, which may suppress immune responses of other CD4+ and CD8+ cells and promote tumour progression." (PMID 26137480, 2015). "CD8+ cytotoxic T lymphocytes, CD4+ T helper (TH) 1 cells and natural killer (NK) cells function as major antitumor effector cells, whereas CD4+ TH2 cells, myeloid-derived suppressor cells (MDSCs) seem to promote tumor progression." (PMID 26462029, 2015). "These experiments also confirm that IL-15 is not required for naive CD4+ T cell homeostasis or tumor rejection in our system." (PMID 26405570, 2015). "Local administration of IL-2 decreased the levels of tumor-infiltrating CD4+ T-cells compared to non-injected control mice." (PMID 26107883, 2015).
tumor (continued). "With regard to our data, more peripheral CXCR5+CD4+ Tfh cells might be recruited to liver tissues in response to the tumor, ultimately leading to a decrease in circulating CXCR5+CD4+ Tfh cells in HCC patients." (PMID 25689070, 2015). "Young hosts exhibited marked tumour eradication regardless of IL-6 blockade when donor CD4+ T cells were primed with peptide-pulsed DCs, whereas as expected the antitumour effect of CD4+ T cells was impaired in control Ab-treated aged mice." (PMID 25850032, 2015). "In agreement with our previous studies in other animal models, depletion of CD4+ T cells in these mice did not affect tumor growth in either WT or AMPK KO mice, suggesting that the AMPK-associated changes in tumor growth were not mediated by CD4+ T cells." (PMID 25760243, 2015). "Vaccination efficacy is LLO dependent and implies the reduction of LLO-specific CD4+ T cell responses, strong stimulation of innate pro-inflammatory immune cells and a prevalence of LLO-specific CD8+ T cells involved in tumour regression and Listeria elimination." (PMID 25760947, 2015). "In murine tumor models with high TAM-infiltration, the administration of an anti-CSF-1R mAb significantly reduced TAMs and simultaneously increased the ratio of cytotoxic CD8+ T cells to CD4+ T cells while decreasing the number of FoxP3+ Tregs." (PMID 25806106, 2015). "Foxp3+CD4+ T cells inhibit the activation of both CD4+ and CD8+ T cells, and within the tumor microenvironment may serve to suppress anti-cancer cell immunity." (PMID 26604855, 2015). "Furthermore, tumor infiltrating lymphocytes surrounding CD70+ tumor cells, showed a trend towards increasing FOXP3 expression and higher CD4/CD8 ratios." (PMID 25951351, 2015). "CXCL10 is a potent chemokine for the recruitment of CD4+ and CD8+ T cells into the tumor sites." (PMID 25605488, 2015). "Here we focus on the impact of this inflammatory environment on T cells, and demonstrate that in contrast to successful tumour elimination in young mice, replenishment of tumour-specific CD4+ T cells fails to induce tumour regression in aged hosts." (PMID 25850032, 2015). "Our results show that the vaccine’s tumor ablative effect requires both CD8+ and CD4+ T-cells." (PMID 26079374, 2015). "The efficacy of antitumor therapy mainly depends on four critical components: the elicited CD8+ Teffs, the quality of the CD4+ helper T cells, the elimination and/or non-activation of Tregs, and the breakdown of the immunosuppressive tumor microenvironment." (PMID 25784913, 2015). "While CD8+ T-em cells are the key effector population that mediate tumor killing, they can be skewed by the tumor environment to develop into regulatory and/or tolerant T cells in the absence of CD4+ T cell help." (PMID 25901284, 2015). "CD8+ T cells, CD4+ T cells, natural killer (NK) cells, and NK T cells secrete interferon- (INF-) γ to inhibit tumor cell proliferation and angiogenesis, whereas macrophages and dendritic cells are processed to phagocytise and remove tumor cells killed." (PMID 26236750, 2015). "While the anti-tumor effect of ACT appears to be primarily mediated by CD8+ effector T cells, CD4+ T cells can also mediate tumor regression and may play a critical role in maintaining long-term immunity and cure of patients." (PMID 26500776, 2015). "Infusion of autologous infiltrating lymphocytes depleting CD4+CD25+ regulatory T cells to BC murine, was capable of increasing activation and proliferation of CD4+ and CD8+ T cells, enhancing IL-4 and IFN-γ secretion, postponing tumor growth and prolonging survival." (PMID 26462021, 2015). "The ability of OX40 agonists to regulate immune responses, as well as the expression of OX40 on CD4 and CD8 lymphocytes from the tumors and tumor-draining lymph nodes in mice and humans, led investigators to examine OX40 manipulation as a treatment for cancer patients." (PMID 25763356, 2015). "It is possible that the generally scarce CD4+ and CD8+ tumor infiltration could hamper mAb efficacy." (PMID 25859247, 2015).
tumor (continued). "Thus, in the in vivo study, we examined the function of DCs in mouse spleens and detected CD4+ and CD8+ T cells in both spleen and tumor tissues." (PMID 25826093, 2015). "CD4+ T cell depletion initially had minimal adverse effect on the therapeutic vaccine strategy and 75% of mice lacking CD4+ T-cells remained tumor free for 4 weeks." (PMID 26079374, 2015). "To find out whether HER-3872−886 peptide is presented on MHC class II molecules on the surface of tumor cells, we cocultured HER-3-reactive CD4 T cells and HLA-DR-matched HER-3-positive tumor cells, and measured IFN-γ production in the culture supernatants." (PMID 26538233, 2015). "Previous studies have demonstrated that the percentage of CD4+ T cells and the ratio of CD4+/CD8+ decreased in patients with PNS, which in turn led to reduced immune function; therefore, the PNS PBMC showed now clear inhibitory effects on tumor cells in vitro." (PMID 25412252, 2015). "The CD4+/CD8+ ratio was the highest in the dLN, followed by the blood and the tumor tissues." (PMID 25605488, 2015). "A subpopulation of CD4+ T cells that express CD25 and the master transcriptional factor Foxp3, termed regulatory T cells (Tregs), play a crucial role in promoting tumor growth and progress by inhibiting anti-tumor CD8+ T cells." (PMID 26451607, 2015). "CD4+ T cells are critical for priming tumor-specific CD8+ T cells, generating and maintaining long-term CD8+ memory T cell responses, and controlling CD8+ T cell trafficking to tumor sites." (PMID 25993655, 2015). "In addition, treatment of CNS tumor-bearing hosts with anti-CD25 mAb delayed the tumor growth and prolonged the survival, suggesting that CCR4+CD4+CD25+ Tregs play an important role in suppressing the immune response to CNS tumors." (PMID 26528477, 2015). "Furthermore, tumor cells pre-incubated with Ara-C stimulated more perforin (MFI: CD8+: 28.24 ± 1.18, CD4+: 16.77 ± 1.35) and granzyme B (MFI: CD8+: 35.47 ± 1.20, CD4+: 22.30 ± 0.40) than tumor cells alone." (PMID 26444983, 2015). "When CD4+ cells are stimulated and maintained, the CD8+ responses are sustained for long periods of time, improving the antitumor response, and potentially leading to the development of long-lasting immunological memory against tumor Ags." (PMID 26807308, 2015). "In one of the study, poor correlation between CD4+CD25+ Tregs and tumor marker AFP was reported." (PMID 25767469, 2015). "LAG-3 and PD-1 are also co-expressed on CD4 and CD8 TILs in various mouse tumor models." (PMID 26347741, 2015). "For example, T cell/B cell conjugate formation rate is reduced and F-actin polymerization at the IS substantially impaired in CD4+ and CD8+ T cells isolated from tumor sites or the blood of leukemic-phase FL patients compared to healthy T cells or circulating T cells from non-leukemic phase FL." (PMID 26082776, 2015). "Second, it may be that pre-mNK cells are activated in the tumor bed, upregulate MHCII, and travel to the draining lymph nodes where they encounter the TRP-1-specific CD4+ T cells." (PMID 26405570, 2015). "Interestingly, even after tumor challenge, the expression levels of total CTLA-4 in CD44hiCD8+ T cells, and the percentages of CD4+Foxp3+ Tregs in lung tumors, spleens, or lymph nodes were not reduced in the immunized SKAP55−/− mice (Fig4F)." (PMID 25851535, 2015). "The antitumour activity of E-cadherin + DCs were evaluated in vivo by promoting the differentiation of effector CD4+ T cells, CEA-specific CD8+ T cells and CD103+ CD8+ T cells and assessing their resistance to tumour challenge, including variations in tumour volume and survival curves." (PMID 25651850, 2015). "Notably, the percentage of CD3+CD4+ T cells and CD3+CD8+ T cells distribution was significantly different in OSCC patients with different tumor size and nodal status." (PMID 26587366, 2015). "ILC-depletion by anti-Thy1.2 antibody fails to improve tumor rejection by adoptively transferred TAA-specific Thy1.1+CD4+ T cells in our model." (PMID 26405570, 2015).
tumor (continued). "By using MHC class I-, MHC class II-, perforin-, B-cell- and IFN-γ- knock-out mice and CD4+ T cell-, CD8+ T cell- and NK cell- depleted mice, we demonstrated that CD4+ T cells and NK cells are the main anti-tumor effectors, and that IFN-γ is a major effector molecule." (PMID 24830315, 2014). "In the current study, we investigated the distribution of CD4+ CD25+ Foxp3+ Tregs in the peripheral blood and regional lymph node lymphocytes during 4NQO-induced rat tongue carcinogenesis and determined their relationships with tumor progression." (PMID 24264641, 2014). "Furthermore, we confirmed that the expression of CD4 and CD8 as well as Foxp3, FR4, CD69, CD154, and CD25 was markedly decreased in the tumor tissues from the tumor-bearing BALB/c nude mice." (PMID 25365349, 2014). "Besides well-known CD8+ and CD4+ T cells, regulatory T cells (Tregs), initially recognized by CD4+ CD25+ profile, are also considered to play an important part in suppressing immune response and promoting tumor invasion." (PMID 24276989, 2014). "This population of CD4+ ICOS-high cells, which was found to be increased in both tumor tissue and peripheral blood, could be a biomarker related to clinical outcome in patients with metastatic disease who received ipilimumab." (PMID 25331657, 2014). "Because percentages of both CD4+ and CD8+ T cells were decreased in mice with larger tumor mass after Tg treatment, we hypothesized that immunosuppressive myeloid cells might have been expanded." (PMID 25514597, 2014). "In addition to a significant increase in CD4+T-lymphocytic infiltrate (P<0.05), RUNX1 positive tumours showed a significant increase in CD138+B- lymphocytic infiltrate (P<0.05) in ER- patients." (PMID 24967588, 2014). "Here, we sought to determine whether peptide vaccines designed harbor both class I as well as class II restricted antigenic motifs could concurrently induce CD4 and CD8 T cell activation against autologous tumor antigens." (PMID 24690990, 2014). "MCF7, PC3, and M628 tumor cell lines were co-cultured with anti-CD3 activated CD4+ T cells in the presence or absence of different TLR ligands, and senescence induction in the treated CD4+ T cells was determined." (PMID 25231413, 2014). "The neoplasm tumor cells exhibit positive CD4, CD56 and CD123 expression, but are negative for CD3, TIA-1 and EBV expression." (PMID 25289105, 2014). "CD4(+) T-cell frequency correlated with tumor size, FoxP3(+) regulatory T-cell (Treg) frequency correlated with lymph node metastasis, and CD8 to Treg ratio inversely correlated with tumor size." (PMID 25328756, 2014). "On the other hand, the basis for antigen presentation and anti-tumor effector mechanisms are less obvious in the context of MHC IINEG tumors – simply because such cancer cells cannot directly stimulate MHC class II-restricted CD4+ T cells." (PMID 24782871, 2014). "This concept was supported by the finding that Th1 cells constituted about 50% of CD4+ cells isolated from either non-tumor or tumor tissues derived from patients with HCC." (PMID 24867183, 2014). "Morphometrically, the average numbers of CD4- and CD8-positive T cells were significantly increased in the tumor stroma, compared with those in the tumor parenchyma (tumor stroma versus tumor parenchyma: 22±3.6 versus 7.4±0.9 in CD4, 32.8±4.2 versus 16±2.5 in CD8; both P<0.01)." (PMID 25289108, 2014). "The scFvMTBHsp70/tumor cell-pulsed DCs induced significantly higher production of IFN-γ and Granzyme B from both CD4+ and CD8+ tumor cell-primed T cells as compared with MTBHsp70 or PBS, indicating that scFvMTBHsp70 enhances tumor antigen presentation and cross-presentation by DCs." (PMID 24565018, 2014). "Anti-CD4 treatment caused tumor recurrence after immunotherapy, but produced no apparent effect in either EMT6 or 4THM tumor bearers after chemotherapy treatment." (PMID 25409195, 2014).